METTL3 (methyltransferase 3, N6-adenosine-methyltransferase complex catalytic subunit)
Diseases named in the same sentence as METTL3 in open-access papers (continued):
Sharing a sentence is not in itself a finding about the gene and the disease.
colorectal cancer (continued). "Besides, compared with normal human colon epithelial cells (FHC), all of the detected human colorectal cancer cell lines showed increased METTL3 expression and upregulated m6A modification levels." (PMID 38001065, 2023). "The expression of methyltransferase-like 3 (METTL3) is increased through SUMO1 SUMOylation modification in colorectal cancer, and increased METTL3 promotes the expression of ABCC1 protein, thus leading to drug resistance of colorectal cancer cells to chemotherapy." (PMID 37777749, 2023). "We then explored whether METTL3 could contribute to colorectal cancer cell metastasis in vivo by establishing a pulmonary metastasis mouse model." (PMID 38001065, 2023). "In colorectal cancer, METTL3 depletion inhibits colorectal tumorigenesis." (PMID 37996892, 2023). "In order to explore the role of METTL3 in regulating tumorigenesis in vivo, colorectal cancer cells with or without METTL3 deficiency were subcutaneously injected into BALB/c nude mice." (PMID 38001065, 2023). "Thus, METTL3 was proved to have an impact on circ1662 formation to drive colorectal cancer metastasis." (PMID 36875073, 2023). "In colorectal cancer, METTL3 inhibits TRAF5 expression by reducing TRAF5 stability." (PMID 37996892, 2023). "Similarly, the total m6A RNA content and expression of METTL3, a key methyltransferase, increased in colorectal cancer tissues of OX-resistant patients." (PMID 36791151, 2023). "For example, METTL3 activated the mA-GLUT1-mTORC1 axis to facilitate colorectal cancer." (PMID 37859814, 2023). "Here, our study has revealed that METTL3 and RNA m6A level was significantly upregulated in colorectal cancer tissues compared with normal tissues, which is consistent with the emerging reports that supported the onco-promoting role of METTL3 and m6A in various cancers." (PMID 38001065, 2023). "However, intestinal bacteria, Fusobacterium nucleatum induced colorectal cancer progression by activating YAP-mediated METTL3 downregulation." (PMID 38001065, 2023). "In addition to lipogenesis and adipogenesis, METTL3 was found to regulate glucose metabolism in colorectal cancer, as METTL3-mediated m6A promoted the mRNA stability of Hk2 and Glut1 in an m6A and IGF2BP2/3-dependent manner." (PMID 35350378, 2022). "Moreover, in colorectal cancer, METTL3 induced the overexpression of circ1662 by binding the flanking sequences through installing its m6A modification." (PMID 35999496, 2022). "Furthermore, a group found that the m6A methyltransferase METTL3 promoted the malignant proliferation of colorectal cancer cells by directly or indirectly upregulating MYC expression." (PMID 35614935, 2022). "In colorectal cancer, METTL3 promotes tumorigenesis by activating the m6A–GLUT1–mTORC1 axis." (PMID 36614956, 2022). "For example, up-regulated METTL3 could promote metastasis of colorectal cancer cells through miR-1246/SPRED2/MAPK signaling pathway." (PMID 36058919, 2022). "Therefore, specific targeting of METTL3 has important application prospects in the treatment of colorectal cancer." (PMID 35614935, 2022). "Knockdown of METTL3 can inhibit the development of colorectal cancer significantly." (PMID 35614935, 2022). "For instance, in hypoxic TME, CAFs alter their exosome content and increase exosome release through metabolic reprogramming, CAF-derived exosomes have been shown to inhibit the sensitivity of colorectal cancer cells to 5-fluorouracil and promote metastasis via the METTL3/miR-181d-5p axis." (PMID 35794625, 2022). "Similarly, targeted inhibition of FTO and METTL3/14 combined with anti-PD-1 based immune checkpoint blockade therapy has been used for leukemia and colorectal cancer." (PMID 35794625, 2022). "In sum, METTL3 modulates the expression and function of various target molecules in a m6A-modified manner to affect the proliferation, apoptosis, metabolism, invasion and metastasis of colorectal cancer cells." (PMID 35614935, 2022).
colorectal cancer (continued). "In addition to the effects on cell proliferation, METTL3 also has relations with the progression and metastasis of colorectal cancer." (PMID 35614935, 2022). "However, the specific function of m6A methyltransferase methyltransferase‐like 3 (METTL3) in colorectal cancer (CRC) remains elusive." (PMID 33411363, 2021). "Decreased METTL3 was found correlated with increased tumor size, advancement and metastasis in colorectal cancer (CRC) where METTL3 downregulation activated the MAPK pathway-associated proteins- particularly p38 and ERK resulting in CRC cell proliferation, migration and invasiveness." (PMID 33814008, 2021). "Targeting METTL3 and its pathway may be promising for treating colorectal cancer patients with high glucose metabolism." (PMID 32245489, 2020). "However, other data suggest converse conclusions about the expression and role of METTL3 in bladder cancer, renal cell carcinoma, colorectal cancer, glioma, and breast cancer." (PMID 31921660, 2019). "Colorectal cancer patients with high METTL3 expression had reduced OS and DFS times." (PMID 31921660, 2019). "Furthermore, METTL3 downregulated LINC01559 expression, and low LINC01559 expression was also associated with TNM stage, lymph node metastasis, and distant metastasis in colorectal cancer patients." (PMID 37781524, 2023). "Therefore, the combination of inhibiting p-STAT3 and METTL3 simultaneously may shed new sight on colorectal cancer therapy." (PMID 38001065, 2023). "In colorectal carcinoma (CRC), METTL3 seems to havea key roleby methylating the transcripts of SOX2, a transcription factor thatenables the maintenance of an undifferentiated state in embryonicand pluripotent stem cells." (PMID 36692498, 2023). "In our previous study, methyltransferase‐like 3 (METTL3) facilitated colorectal carcinoma (CRC) progression through increasing SOX2 expression to maintain the CRC stemness phenotype in an m6A‐IGF2BP2‐dependent machinery." (PMID 38082402, 2023). "Interestingly, in colorectal cancer and melanoma, enhanced anti-PD-1 efficacy could be achieved by depletion of METTL3 and METTL14, potentially via increased CD8+ T-cell infiltration and tumor killing function." (PMID 35794625, 2022). "For example, METTL3 expression is elevated in breast cancer tissues and cells and can promote the multiplication of breast cancer cells and inhibit apoptosis by targeting Bcl-2; METTL3 upregulation promotes the metastasis of colorectal cancer cells through miR-1246/SPRED2/MAPK signaling pathway." (PMID 33818282, 2021). "The m6A modification catalyzed by Mettl3 has been proven to control specific target mRNAs translation efficiency and stability, which plays a key role in promoting progression of various cancers including lung cancer, endometrial cancer, leukemia, and colorectal cancer." (PMID 33681207, 2021). "In addition, METTL3 is also shown to induce colorectal cancer relying on glycolysis." (PMID 33552994, 2020). "For example, in colorectal cancer, elevated lactate levels induce H3K18 lactylation and direct lactylation of methyltransferase-like 3 (METTL3) at RNA-binding zinc-finger domains, enhancing its ability to catalyze m6A modification of JAK1 mRNA." (PMID 41491598, 2026). "METTL3 plays a key role in replicating senescence of colorectal cancer (CRC) cells, and inhibition of METTL3 or targeted inhibition of CDKN2B methylation can effectively inhibit CRC senescence." (PMID 40092631, 2025). "Conversely, in colorectal cancer (CRC), inhibition of METTL3 has shown significant antitumor effects." (PMID 40867324, 2025). "In colorectal cancer, which is characterized by elevated METTL3 and HIF-1α levels, METTL3 knockdown reduced the m6A modification of HIF1A and lowered its translation efficiency, leading to the suppression of the Warburg effect." (PMID 40102715, 2025). "Overall, our findings suggest the METTL3/STC2 axis as a promising therapeutic target to combat drug resistance and metastasis in colorectal cancer." (PMID 40494964, 2025).
colorectal cancer (continued). "This study aims to elucidate the role of m6A modification in colorectal cancer (CRC), focusing on the effect of METTL3 on STC2 expression and its effects on cell proliferation, drug resistance and metastasis." (PMID 40494964, 2025). "For example, in colorectal cancer, ALKBH1‐mediated m1A demethylation of METTL3 mRNA promotes metastasis by downregulating SMAD7 expression." (PMID 41017026, 2025). "Specifically, high METTL3 and YTHDF1 expression is detected in neoplastic tissues from colorectal cancer patients with pulmonary metastases." (PMID 40986143, 2025). "This study revealed that METTL3 and YTHDF1 are highly expressed in tumors from patients with colorectal cancer lung metastasis." (PMID 40356596, 2025). "METTL3 catalyzes the m6A modification of lncRNA SNHG1, enhancing its RNA stability and subsequently driving tumorigenic proliferation of colorectal cancer cells." (PMID 40986143, 2025). "Similar to other tumors, the regulation of m6A modifications in colorectal cancer is equally diverse and complex, and almost all m6A modifiers except METTL14, ZC3H13, METTL3, FTO, ALKBH5, and YTHDF2 promote colorectal carcinogenesis." (PMID 39967906, 2025). "For instance, METTL3 can induce GLUT1 mRNA translation and facilitate glucose uptake and lactate generation, thus activating mTORC1 signaling in colorectal cancer." (PMID 38902779, 2024). "For example, METTL3 induces m6A modifications on GLUT1 mRNA, enhancing glucose uptake and lactate production, which in turn activates mTORC1 signaling and promotes colorectal cancer progression." (PMID 39695216, 2024). "Targeting regulators such as METTL3, METTL14, IGF2BP3, or YTHDF1 can alleviate T-cell suppression in melanoma, colorectal cancer, non-small cell lung cancer (NSCLC), and breast cancer." (PMID 39372415, 2024). "In colorectal cancer (CRC), high expression of METTL3 promotes the proliferation, migration, and invasive process of CRC cells." (PMID 39289775, 2024). "The study revealed high expression of METTL3 and YTHDF1 in the tumors of patients with pulmonary metastasis of colorectal cancer." (PMID 38605400, 2024). "Chen showed that METTL3 induced GLUT1 translation to promote glucose uptake and colorectal cancer development." (PMID 38845937, 2024). "A similar conclusion was made for colorectal cancer (CRC), where METTL3 was found to suppress cell proliferation, migration, and invasion through p38/ERK pathways and thus supported patients’ longer survival time." (PMID 38966069, 2024). "The molecular mechanism utilized by METTL3 to regulate JAK1 and STAT3 expressions has been elucidated in colorectal cancer cells, but the downstream effector that orchestrated JAK/STAT3 signaling function in cancer cells is still obscure." (PMID 38001065, 2023). "Mechanistically, METTL3 upregulates circQSOX1 via m6A methylation, and circQSOX1 indirectly promotes PGAM1 expression through sponge miR-326 and miR-330-5p to make colorectal cancer cells exhibit resistance to immunotherapy." (PMID 37781524, 2023). "In colorectal cancer (CRC), METTL3 promotes GLUT1 translation to induce glucose uptake and lactate production and activates mammalian target of rapamycin complex 1(mTORC1) signaling, which results in cancer development." (PMID 37055798, 2023). "m6A circNSUN2 regulates cytoplasmic export and stabilizes HMGA2 to promote colorectal carcinoma (CRC) liver metastasis (LM); In colorectal cancer, another METTL3-induced circ1662 promoted CRC cell invasion and migration by accelerating YAP1 nuclear transport." (PMID 36861189, 2023). "In colorectal carcinoma (CRC), METTL3 promotes stemness and tumor progression by regulating the expression of SOX2 through an m6A-IGF2BP2-dependent mechanism." (PMID 38012755, 2023). "METTL3 stabilizes HK2 and SLC2A1 (GLUT1) expression in colorectal cancer and m6A-dependent glycolysis enhances colorectal cancer progression." (PMID 36249071, 2022).
colorectal cancer (continued). "The “writer” protein METTL3 can methylate and stabilize SRY sex-determining region Y (SRY)-box 2 (SOX2) mRNA, which promotes the invasion and migration of colorectal cancer cells." (PMID 36226062, 2022). "METTL3 stabilizes GLUT1 and HK2 mRNA in colorectal cancer by directly interacting with the 3′ UTR mRNA of GLUT1 and the 5'/3′-UTRs mRNA of HK2." (PMID 35186927, 2022). "Research have suggested that METTL3 targets the YPEL5 m6A modification site to inhibit its expression and promote the progression of colorectal cancer." (PMID 35614935, 2022). "METTL3 can promote activation of MAPK by promoting the methylation of pri-miR-1246 and targeting SPRED2 in colorectal cancer." (PMID 35022030, 2022). "As a promising predictor in colorectal cancer diagnosis, exosomal circLPAR1 suppresses colorectal cancer development through decreasing BRD4 via METTL3-eIF3h interaction." (PMID 36814375, 2022). "Previous research has identified METTL3 and METTL14 are m6A methylation writers on mRNAs, which regulate the growth and metastasis of renal cancer, colorectal cancer, pancreatic cancer, and other cancers." (PMID 36311770, 2022). "More subsequent studies have also demonstrated that METTL3 is significantly upregulated in hepatocellular carcinoma (HCC), colorectal cancer (CRC), retinoblastoma (RB), and multiple solid tumors." (PMID 36226062, 2022). "Another study has confirmed that METTL3 carries out m6A modification on GLUT1 mRNA to improve its mRNA stability and translation level, and promote glucose metabolism and colorectal cancer occurrence." (PMID 35614935, 2022). "For example, 3-deazaadenosine inhibits METTL3/METTL14, CA4 (carbonic anhydrase member) induces WTAP degradation and suppresses colorectal cancer proliferation, and R-2-hydroxyglutarate (R-2HG) delays leukemia progression via inhibition of FTO." (PMID 35794625, 2022). "proved that METTL3 upregulates SOX2 expression through IGF2BP2 to recognize and increase the stability of SOX2 mRNA and promote colorectal carcinoma cell self-renewal, increase stem cell frequency and promote migration in a m6A-dependent manner." (PMID 35299748, 2022). "For instance, expression of METTL3 in macrophages was suggested to synergize with PD-1-based therapy in B16 melanoma, and METTL3 and METTL14 have been shown to regulate immune response to anti-PD-1 treatment in melanoma and colorectal carcinoma." (PMID 35558067, 2022). "The expression level of these m6A regulatory proteins such as METTL3, FTO, YTHDF2 have been found to be dysregulated in a variety of cancers, including lung cancer, colorectal cancer, breast cancer and GC, etc.." (PMID 34702266, 2021). "Further, the simultaneous suppression of METTL3 and METTL14 has also been demonstrated to augment the efficacy of anti‐PD‐1 therapy in colorectal cancer and melanoma, owing to the higher infiltration of CD8+ T cells and massive cytokine release in the TIME." (PMID 34586737, 2021). "Intriguingly, the efficacy of anti‐PD‐1 is considerably augmented by simultaneous depletion of METTL3 and METTL14 in both colorectal cancer and melanoma." (PMID 34586737, 2021). "METTL3 has been shown to induce GLUT1 translation to activate the m6A-GLUT1-mTORC1 axis and promote colorectal cancer (CRC) progression." (PMID 34315512, 2021). "Moreover, overexpression of METTL3 significantly suppresses proliferation, migration, and invasion of colorectal carcinoma (CRC) cells." (PMID 33795529, 2021). "One study revealed the basic functions of m6A in colorectal carcinoma (CRC) and demonstrated the carcinogenic effects of METTL3 in promoting stemness and metastasis of CRC." (PMID 34745269, 2021). "For example, in colorectal carcinoma, SOX2 promotes cancer through methylation catalyzed by METTL3, while in breast cancer, BNIP3 promotes the cancer through demethylation catalyzed by FTO." (PMID 34489709, 2021).
colorectal cancer (continued). "In contrast, however, METTL3 interaction with the p38/ERK pathway inhibits the proliferative, migratory, and invasive capacities of colorectal carcinoma cells." (PMID 34105069, 2021). "As the m6A target of METTL3 found in this study, TFAP2C was found to potentiate chemoresistance, which is consistent with the findings in colorectal cancer." (PMID 32857912, 2020). "METTL3 and IGF2BP2 (insulinlike growth factor 2 MRNA-binding protein 2) were overexpressed in colorectal cancer and promote the cancer progression." (PMID 33575259, 2020). "In this context, the METTL3/miR-1246/SPRED2 axis plays an important role and provides a new m6A modification mode for the development of colorectal cancer." (PMID 33552994, 2020). "The m6A “writers” METTL3 and m6A “readers” IGF2BP2/3 were found to participate in the methylation of VEGFA to prevent mRNA degradation, and to promote angiogenesis in colorectal cancer by mimicking the formation of the PI3K/AKT/mTOR and ERK1/2 signaling pathways." (PMID 40316995, 2025). "Additionally, through sequencing and clinical sample testing, we observed elevated expression levels of METTL3 and YTHDF1 in samples of colorectal cancer lung metastasis." (PMID 38605400, 2024). "Besides, ALKBH5, FTO, METTL3, METTL14, METTL16 and WTAP were detected in a section of colorectal cancer tissue." (PMID 39039912, 2024). "Targeting regulators like METTL3, METTL14, the IGF2BP family, ALKBH5, or FTO can enhance the efficacy of PD-1 blockade therapy in renal clear cell carcinoma, colorectal cancer, melanoma, NSCLC, breast cancer, hepatocellular carcinoma, and intrahepatic cholangiocarcinoma." (PMID 39372415, 2024). "Additionally, through WB and IHC experiments, we further confirmed the high expression of METTL3 and YTHDF1 in colorectal cancer lung metastases." (PMID 38605400, 2024). "Exosomal circLPAR1 and methyltransferase-like 3 (METTL3) competitively bind RBP eIF3h, effectively reducing the translation of brominated protein 4 (BRD4) and subsequently inhibiting the proliferation, invasion, and migration of colorectal cancer cells." (PMID 37168995, 2023). "Notably, METTL3 promotes the expression of BHLHE41 in an m6A-dependent manner and subsequently induces CXCL1 transcription to promote colorectal cancer." (PMID 37020540, 2023). "In colorectal cancer, FOXD3 acts as a transcription activator to increase METTL3 expression." (PMID 37996892, 2023). "In concert with IGF2BP2, METTL3 promotes m6A modification of the SOX2 CDS region to inhibit SOX2 RNA degradation, which increases the protein content of intracellular SOX2 and induces colorectal cancer metastasis." (PMID 37996892, 2023). "In CRC cells, METTL3 is an oncogene that stabilizes HK2 as well as GLUT1 expression via IGF2BP2- or IGF2BP2/3-related mechanisms and activates the subsequent aerobic glycolysis pathway to boost colorectal cancer progression." (PMID 37055798, 2023). "Besides, a novel METTL3-induced circRNA, circRNA circ1662, exhibits significantly higher expression in colorectal carcinoma (CRC) and circ1662 could promote cellular invasion and migration in vitro and in vivo." (PMID 36781839, 2023). "METTL3 depletion promotes STAT1 and IRF1 mRNA expression in an m6A-YTHDF2-dependent manner, which in turn improves immunotherapeutic response by modulation of tumor-infiltrating cells in the intratumor microenvironment of colorectal cancer." (PMID 35197058, 2022). "SOX2 is identified as a downstream target of METTL3, and METTL3 is reported to maintain the expression of SOX2 by facilitating its methylation, thereby leading to the progression of glioma and colorectal cancer." (PMID 35467477, 2022). "As METTL3 depletion can decline oncogenes’ expression and reduce CRC proliferation, breast cancer, cervical cancer, and liver cancer, METTL3 offers an alternative therapeutic target in colorectal cancer patients with high glucose levels." (PMID 35186927, 2022).